TGM3 (transglutaminase 3)
Diseases named in the same sentence as TGM3 in open-access papers (continued):
Sharing a sentence is not in itself a finding about the gene and the disease.
TGM3 also shares sentences with these, for which no sentence is quoted: basal cell carcinoma (2 papers); oral squamous cell carcinoma (2); adenocarcinoma (1); Alzheimer disease (1); autism (1); autoimmune disease (1); breast invasive carcinoma (1); breast tumors (1); cholangiocarcinoma (1); colon adenocarcinoma (1); epithelial neoplasm (1); Giardia infection (1); hair disorder (1); Hyperkeratosis (1); immune deficiency (1); lung carcinoma (1); lung squamous cell carcinoma (1); lymphatic malformation (1); malaria (1); memory impairment (1); metastasis (1); nicotine dependence (1); prostate adenocarcinoma (1); sarcoidosis (1); schizophrenia (1); sensitivity (1); stenosis (1); uterine corpus endometrial carcinoma (1); Wilms tumor (1).